DKK3 (dickkopf Wnt signaling pathway inhibitor 3)
Diseases named in the same sentence as DKK3 in open-access papers (continued):
Sharing a sentence is not in itself a finding about the gene and the disease.
breast cancer (continued). "Additionally, DKK3 and ITIH5 specificity in colon cancer cfDNA is much higher in comparison to RASSF1A, indicating the eligibility of DKK3 and ITIH5 as potential breast cancer biomarkers." (PMID 23320751, 2013). "Recently, DKK3 was also reported frequently silenced as a valuable biomarker for breast cancer in the European population, but without detailed mechanistic study." (PMID 23890219, 2013). "Tumor-specific methylation of the three-gene panel (ITIH5, DKK3, and RASSF1A) might be a valuable biomarker for the early detection of breast cancer." (PMID 23320751, 2013). "The combination of DKK3 and ITIH5 methylation revealed a sensitivity of 39.9% (55 of 138) for the detection of breast cancer and a specificity of 93.3% (126 of 135) and of 97.4% (38 of 39) in healthy controls and benign disease controls (P < 0.0001), respectively." (PMID 23320751, 2013). "MSP analysis revealed that both DKK2 (data not shown) and DKK3 methylation were frequently detected in breast cancer lines." (PMID 23890219, 2013). "Multivariate analyses revealed that DKK3 methylation was an independent prognostic factor predicting poor OS (hazard ratio (HR): 14.4; 95% confidence interval (CI): 1.9–111.6; p = 0.011), and short DFS (HR: 2.5; 95% CI: 1.0–6.0; p = 0.047) in breast cancer." (PMID 19570204, 2009). "Preliminary results from our laboratory revealed that DKK3 methylation can be detected with high clinical sensitivity and specificity in blood serum of breast cancer patients independent of tumor size and node status (unpublished data)." (PMID 19570204, 2009). "To start our analysis of DKK3 expression in breast cancer patients we analysed mRNA expression in non-malignant and malignant breast cell lines using realtime PCR." (PMID 18826564, 2008). "To further support this data set we analysed 40 additional breast carcinomas with no corresponding normal breast tissue and referred each individual DKK3 mRNA expression level to the mean DKK3 expression of the previously analysed 19 normal breast tissues." (PMID 18826564, 2008). "Our observation that both PD-L1 and CMTM6 were highly expressed in the breast cancer triple-negative MDA-MB-231 cells, a cell line widely used in PD-L1 studies, led us to use these cells to examine the half-life of PD-L1 after stimulation of the cells with REIC/Dkk-3." (PMID 36869893, 2023). "However, the biological function of DKK3 in the intrinsic breast cancer subtypes has not been analyzed so far." (PMID 27467270, 2016). "However, the functional impact of DKK3 on the tumorigenesis of distinct molecular breast cancer subtypes has not been considered so far." (PMID 27467270, 2016). "However, a subtype-specific expression analysis for DKK3 in breast cancer has not been performed so far." (PMID 27467270, 2016). "However, a direct correlation of DKK3 expression and patient survival in the different molecular subtypes of breast cancer has not been analyzed so far." (PMID 27467270, 2016). "However, to the authors' knowledge, a comprehensive study on DKK3 gene regulation and its implication in breast cancer has not yet been published." (PMID 18826564, 2008). "As an additional control that infiltrating immune cells do not contribute to methylation signals in mammary tumours, bisulphite-converted DNA from human peripheral blood lymphocytes were assayed and revealed an unmethylated DKK3 promoter, consistent with results from a previous study." (PMID 18826564, 2008). "Although role of DKK3 in regulating WNT signaling was not clear, recently DKK3 is shown to inhibit canonical WNT signaling in lung and breast cancer cells." (PMID 23667645, 2013). "We here demonstrate for the first time that DKK3 methylation, but not WIF1 methylation, is an independent prognostic factor indicating poor patient survival in human breast cancer." (PMID 19570204, 2009).
gastric cancer (22 papers, 2008 to 2026). A primary or metastatic malignant neoplasm involving the stomach. "The methylation inactivation of tumor suppressor DKK3 was linked with pathogenesis of gastric cancer.The loss of DKK3 was responsible for the progression of EOC.The loss of GSTT1 was responsible for the inactivation of the detoxification processes in EOC." (PMID 30970615, 2019). "In addition, compared to that observed in patients with strong DKK3 expression, DKK3 downregulation in tumors of gastric cancer tissue samples was associated with short disease-free survival." (PMID 35205672, 2022). "Moreover, serum Dkk3 concentration has been reported as remarkably higher in age-matched controls than in gastric cancer patients, where it was inversely associated with tumor size." (PMID 33425757, 2020). "On the other hand, DKK 3 and CD 276 are new markers currently being studied for their prognostic role in gastric cancer and beyond." (PMID 41153243, 2025). "This, together with the induced Tbx3 and suppressed Dkk3, suggested that the aged gastric organoids in the current study possibly possessed the potential to develop gastric cancer." (PMID 36923312, 2022). "Accumulating evidence indicates that gastric cancer has lower levels of DKK-3 and its methylation is a very common event in gastric and colorectal cancers." (PMID 34124998, 2021). "E2F3 is highly expressed in gastric carcinoma tissues and regulates DKK3 expression by modulating miR-125a expression, ultimately promoting gastric cancer cell proliferation, migration, and invasion." (PMID 34657558, 2021). "The data demonstrate that the expression of DKK-3 was obviously lower in gastric cancer cell lines than normal cells." (PMID 34124998, 2021). "Previously, we observed that the presence of Dkk3 overexpression and recombinant Dkk3 triggered G1 phase arrest in gastric cancer cells by downregulating Cyclin D2 and Cyclin E expression via the Wnt/β-catenin pathway." (PMID 33425757, 2020). "Immunohistochemically, the level of Dkk3 expression was inversely correlated with tumor size, lymph node involvement, cell dedifferentiation, and unfavorable prognosis in gastric cancer." (PMID 33425757, 2020). "To investigate the biological role of DKK3 in gastric cancer, we first examined the expression of DKK3 in tissue slices." (PMID 31423109, 2019). "It was found that DKK3 mRNA was highly expressed in normal tissues, moderately expressed in para-carcinoma tissues and weakly expressed in gastric cancer tissue." (PMID 31423109, 2019). "Equivalent tumor suppressive property on DKK3 downregulation is exhibited in hepatocellular carcinoma, cervical cancer, gastric cancer, and non-small-cell lung carcinomas cells." (PMID 31737564, 2019). "For all of our validated genes of interest (VAV3, TWIST1 and DKK3), it has previously been established that the level of the mRNA expression is representative for its protein level, in pulmonary fibrosis, gastric cancer and various cell lines." (PMID 20976069, 2010). "Because the enhanced Tbx3 expression seen in aged gastric organoids was also observed in human gastric cancer tissues, this Dkk3-Wnt-Tbx3 pathway may be involved in aging-related gastric carcinogenesis." (PMID 36923312, 2022). "Hence, the pathologic mechanism of miR-425 and its correlation with DKK-3 in gastric cancer is urgent to figure out." (PMID 34124998, 2021). "In addition, we found higher supernatant Dkk3 level in Dkk3 transfectants of colorectal and gastric cancer cells." (PMID 33425757, 2020). "In gastric cancer, Dkk3 overexpression or Dkk3 treatment decreased the karyoplasmic ratio, cell proliferation, migration, invasion, and lamellipodia formation and increased the likelihood of G1 phase arrest and apoptosis, which were blocked by anti-Dkk3 antibody." (PMID 33425757, 2020).
gastric cancer (continued). "DKK3 methylation is associated with reduced DFS in acute lymphoblastic leukemia, and also with shorter OS in kidney cancer and non-small cell lung cancer, as well as very recently reported with OS in gastric cancer." (PMID 19570204, 2009). "Interestingly, while DKK-3 has been recognised as a tumour suppressor in various cancers, such as prostate and gastric carcinomas, recent studies suggest an oncogenic role of DKK-3 in head and neck squamous cell carcinoma, with higher expression levels correlating with poorer prognosis." (PMID 41007216, 2025). "WIF1 and DKK3 to poor prognosis in breast cancer; FGR3 mutation and hypermethylation to bladder cancer and SFRP2 hypermethylation to gastric cancer (GC)." (PMID 27050149, 2016). "On the other hand, DKK3 showed a reciprocal expression to TBX3 (2.20 ± 0.06 in oxyntic glands, 1.75 ± 0.06 in atrophic gastritis, 0.52 ± 0.14 in gastric cancer)." (PMID 36923312, 2022). "Notably, methylation of the DKK3 promoter was recently shown to be prognosis relevant also in other tumor entities, such as in acute lymphoblastic leukemia, kidney cancer, lung cancer, and gastric cancer, pointing to a potential clinical use of this marker in several cancer diseases." (PMID 19570204, 2009). "Also, the promoter region hypermethylation of Dkk-3, CDH-5, DDAPK, p16, and RASSF1A genes are individual biomarkers useful in predicting the clinical features of gastric cancer patients." (PMID 28144288, 2017). "RASSF1A, p14ARF, and MGMT; CHRNA3, DOK1, and GNMT; p16, hMLH1, MINT1, MINT2, MINT12, MINT25, and MINT31; APC, CDH1, MHL1, CDKN2A, CDKN2B, and RUNX3; CDH1; DKK3; PTEN; MGMT; TFPI2; CACNA2D3; PCDH10; SOX2; MAL; and COX2 were previously reported to be hypermethylated in gastric cancer." (PMID 26121593, 2015). "Although new markers such as Human Dickkopf Related Protein 3 (DKK3) and Human Cluster of Differentiation 276 (CD 276) have been discovered, which may be useful in assessing the prognosis of gastric cancer patients, their role in postoperative follow-up is not yet elucidated." (PMID 41153243, 2025).
melanoma (22 papers, 2009 to 2023). A malignant, usually aggressive tumor composed of atypical, neoplastic melanocytes. "We also point out other mechanisms here that may contribute to DKK1 and DKK3 gene (and consequently DKK1 and DKK3 protein) silencing, such as the mutational burden and various miRNAs, as recently shown in a case of melanoma and colorectal cancer." (PMID 34064046, 2021). "Evidence has shown that miR-942-5p accelerates human melanoma cell growth by reducing DKK3 expression." (PMID 34872448, 2021). "LINC00459 downregulated in melanoma sponges miR-218 which in turn downregulates dickkopf WNT signaling pathway inhibitor 3 (DKK3)." (PMID 34638331, 2021). "DKK3 inhibition in melanoma cells results in the upregulation of nuclear β-catenin, whereas upregulation of DKK3 partially attenuates the oncogenic effects of miR-25 in melanoma cells." (PMID 30866509, 2019). "LINC00459/miR-218/DKK3 pathway has enriched the mechanism of development of melanoma to some extent." (PMID 31844121, 2019). "miR-25 activated the WNT pathway by targeting DKK3, thus not only enhancing the ability of melanoma to infiltrate into tumor tissue but also facilitating tumor invasion and metastasis by upregulating TCF4, c-Myc, and Cyclin D1 in vitro and in vivo." (PMID 27801786, 2016). "Our findings suggest that miR-25 promotes melanoma cell proliferation and motility partially by targeting DKK3." (PMID 27801786, 2016). "In summary, miR-25 is upregulated in melanoma and promotes melanoma cell proliferation and invasion, partially by targeting DKK3." (PMID 27801786, 2016). "Irradiation with 2 Gy led to the up-regulation of DR5 and DKK3 in A375 melanoma cells and up-regulation of DKK3in G361." (PMID 26378036, 2015). "Dkk-3 has been shown to support tube formation in primary endothelial colony-forming cells and DKK3 overexpression reduced ANGPT1 expression in a murine B16F10 melanoma model." (PMID 23765731, 2013). "DKK3 expression is usually lost at early stages of melanoma development." (PMID 34638331, 2021). "Moreover, Dkk3 expression enhanced cellular adhesion and reduced the rate of cellular migration of melanoma cells." (PMID 33425757, 2020). "Moreover, the up-regulation of miR-218 in melanoma cells had reversal effect on the inhibition of cell viability, invasion and migration induced by DKK3 overexpression." (PMID 31844121, 2019). "LINC00459 may act as an endogenous competitive RNA to sponge miR-218 and thus moderate the effector DKK3 to regulate the proliferation and migration of melanoma." (PMID 31844121, 2019). "In conclusion, our research results indicate that the LINC00459/miR-218/DKK3 pathway may be a novel therapeutic target and biomarker in melanoma." (PMID 31844121, 2019). "The MTT, wound-healing, and transwell migration assays indicated that DKK3 supplementation could dramatically attenuate the effect of miR-25 on melanoma cells." (PMID 27801786, 2016). "The data suggested that miR-25 and DKK3 overexpression could regulate the expression of these genes in melanoma." (PMID 27801786, 2016). "Upregulation of DKK3 partially attenuated the oncogenic effect of miR-25 on melanoma cells." (PMID 27801786, 2016). "DKK3 has been shown to be inhibited by miR-25 in melanoma in our study." (PMID 27801786, 2016). "The miR-25/DKK3 axis provides new insight into the pathogenesis of melanoma, particularly with respect to proliferation and metastasis, and it represents a potential therapeutic target for melanoma." (PMID 27801786, 2016). "DKK1 and DKK2 were undetectable in B16F10 melanoma cells, whereas DKK3 and DKK4 were expressed." (PMID 24091497, 2014). "In melanoma mouse model, highly expressed DKK-3 could enhance the micro vessel density remarkable." (PMID 34124998, 2021). "To better understand the mechanism that LINC00459 impacts progression of melanoma, we further identified and validated LINC00459/miR-218/DKK3 pathway that regulated the proliferation and invasion ability of melanoma cells." (PMID 31844121, 2019).
melanoma (continued). "The expression of DKK3 is low in malignant melanoma, and DKK-3-transfected cells revealed that DKK3 upregulated cell-cell adhesion and downregulated cell migration." (PMID 27801786, 2016). "MSCs were derived from bone marrow of EGFP+ C57BL/6 or EGFP+ DKK3−/− mice and inoculated into C57BL/6 mice together with HCmel12 melanoma cells." (PMID 26734010, 2015). "Besides the prostate elevated Dkk-3 expression has also been shown in vessels from other tumors for example in colorectal cancer, glioma, non-Hodgkin lymphoma, melanoma, and pancreatic adenocarcinoma whereas vessels from normal tissue express low/not detectable Dkk-3 levels 33,34." (PMID 23765731, 2013).
glioma (21 papers, 2009 to 2025). A benign or malignant brain and spinal cord tumor that arises from glial cells (astrocytes, oligodendrocytes, ependymal cells). "The Dickkopf-3 (DKK3) gene shows the ability to inhibit the activation of the WNT pathway implicated in glioma proliferation and invasion." (PMID 40002166, 2025). "Using the TCGA database, we recently reported an association between glioblastoma (a grade IV glioma) and the DKK3 gene involved in Wnt/β-catenin signaling." (PMID 38672212, 2024). "The aim of this study was to compare the association of DKK3 with other Wnt/β-catenin pathway-related genes and immune responses between lower grade glioma (LGG) and GBM." (PMID 37149563, 2023). "Linear regression analysis was performed to identify the association between DKK3 expression and immune cell fractions in all grade II to IV gliomas." (PMID 37149563, 2023). "Our results demonstrated that Dkk-3 was significantly reduced in glioma cell lines and in human GBM samples, observing lower levels in malignant human glioma cell lines (U-138MG and A-172), so underling the down regulation of Dkk-3 in growth." (PMID 30680070, 2018). "The molecular mechanisms underlying the tumor-suppressing function of REIC/Dkk-3 in human glioma remain obscure." (PMID 28978116, 2017). "Therefore, we hypothesized that high DKK3 expression may be associated with an immunosuppressive GBM microenvironment and that the association between DKK3 expression and immune responses may be altered according to the grade of glioma." (PMID 37149563, 2023). "Therefore, we subsequently wanted to investigate whether DKK3 expression is also associated with immunosuppression and prognosis in lower grade glioma (LGG) using the Cancer Genome Atlas (TCGA) database in this study." (PMID 37149563, 2023). "We also observed that as the grade of glioma increased, DKK3 expression showed a tendency to be more strongly positively correlated with the expression of CTNNB1, FSTL1, and CSNK1A1, which are related to the Wnt/β-catenin pathway." (PMID 37149563, 2023). "We identified linear associations between the expression of the DKK3, CTNNB1, FSTL1, and CSNK1A1 genes classified by the WHO glioma grade." (PMID 37149563, 2023). "We observed an overall significant positive association between DKK3 expression and the CD8 + T-cell fraction with a LOWESS curve showing a curvilinear relationship in all grade II to IV gliomas." (PMID 37149563, 2023). "According to our findings, under grade II or III glioma conditions, the function of DKK3 to suppress Wnt/β-catenin signaling seems to be somewhat inhibited." (PMID 37149563, 2023). "As the grade of glioma increased, DKK3 showed a tendency to be more strongly positively correlated with the expression of other Wnt/β-catenin pathway-related genes." (PMID 37149563, 2023). "In grade II and III glioma, DKK3 showed a significant positive correlation with CD8 + T cells and memory B cells." (PMID 37149563, 2023). "Recently, we demonstrated the anti-glioma effects of an adenoviral vector carrying REIC/Dkk-3 with the super gene expression system (Ad-SGE-REIC)." (PMID 36006934, 2022). "Further, the miR-92b-3p inhibitor has been shown to promote glioma cell apoptosis, by targeting Dkk3 and blocking the Wnt/beta-catenin signaling pathway." (PMID 29116117, 2017). "This study showed a significant decrease of glioma cells as consequence of an up-regulation of Dkk-3." (PMID 28978116, 2017). "Probably it is related to REIC/Dkk-3 that regulates the growth and survival of glioma cells by caspase-dependent and -independent mechanisms, via modification of the Wnt signaling pathway." (PMID 28978116, 2017). "In another, recent, study has documented the effectiveness of Dkk-3 as a tumor-suppressor in glioma cell lines (U87ΔEGFR and GL261)." (PMID 28978116, 2017). "In an interesting study it was shown that down-regulation of Dkk-3 is a key event in the progression of gliomas." (PMID 28978116, 2017).